TDRD3 (tudor domain containing 3)
Description:
Scaffolding protein that specifically recognizes and binds dimethylarginine-containing proteins. Plays a role in the regulation of translation of target mRNAs by binding Arg/Gly-rich motifs (GAR) in dimethylarginine-containing proteins. In nucleus, acts as a coactivator: recognizes and binds asymmetric dimethylation on the core histone tails associated with transcriptional activation (H3R17me2a and H4R3me2a) and recruits proteins at these arginine-methylated loci. In cytoplasm, acts as an antiviral factor that participates in the assembly of stress granules together with G3BP1.
Synonyms: FLJ21007
Tractability: Small molecule: a structure with a bound ligand is known. PROTAC: UniProt records ubiquitination sites on it; ubiquitination databases record sites on it; its protein half-life has been measured.
Target class: Methyl-lysine/arginine binding protein; Reader; Epigenetic regulator; Tudor domain
Gene: Protein-coding gene on chromosome 13 (60,396,457 to 60,573,879, forward strand). Ensembl gene ENSG00000083544.
Subcellular location: Cytoplasm; Nucleus
Subcellular location (Human Protein Atlas): Nucleoplasm; Cytosol; Golgi apparatus
Gene Ontology:
Molecular function: chromatin binding; histone H3 reader activity; histone H4 reader activity; protein binding; RNA binding; transcription coactivator activity
Biological process: siRNA-mediated heterochromatin formation; positive regulation of DNA-templated transcription
Cellular component: cytoplasm; cytosol; exon-exon junction complex; nucleoplasm; nucleus; DNA topoisomerase III-beta-TDRD3 complex
Genetic constraint (gnomAD): Loss-of-function variants: 43 observed, 81.26 expected, observed/expected ratio (o/e) 0.53, 90% interval 0.41 to 0.68. The upper end of that interval is the gene's LOEUF score, 0.68, which puts it in group 2 of 6, group 1 being the genes least tolerant of losing a copy. Missense variants: 753 observed, 859.33 expected, observed/expected ratio (o/e) 0.88, 90% interval 0.82 to 0.93. Synonymous variants: 274 observed, 290.95 expected, observed/expected ratio (o/e) 0.94, 90% interval 0.85 to 1.04.
Homologues: Orthologues: chimpanzee TDRD3 (99% identical), macaque TDRD3 (96% identical), rabbit TDRD3 (93% identical), pig TDRD3 (92% identical), dog TDRD3 (88% identical), rat Tdrd3 (87% identical), mouse Tdrd3 (85% identical), guinea pig TDRD3 (83% identical), tropical clawed frog tdrd3 (60% identical), zebrafish tdrd3 (51% identical), Drosophila melanogaster Tdrd3 (28% identical), Caenorhabditis elegans Y50D4C.3 (22% identical).
Diseases named in the same sentence as TDRD3 in open-access papers:
TDRD3 is named in the same sentence as 25 diseases in open-access papers, as found by Europe PMC text mining. Sharing a sentence is not in itself a finding about the gene and the disease. The quoted sentences say what the papers report.
breast carcinoma (6 papers, 2014 to 2023). "In order to gain mechanistic insight into the function of TDRD3 in promoting breast cancer cell invasion, and to mitigate the possibility of any off-target effects of shRNAs, TDRD3 expression was rescued in MDA MB 231 TDRD3 deficient cells." (PMID 28698590, 2017). "Our results show that TDRD3’s ability to recognize dimethyl arginine residues is required to rescue efficient breast cancer cell invasive potential as ΔTudor or E691K mutant alleles were not able to rescue invasion." (PMID 28698590, 2017). "Furthermore, we show that TDRD3 regulates the expression of a number of key genes associated with promotion of breast cancer tumorigenesis and disease progression." (PMID 28698590, 2017). "Previously, we generated an MDA-MB-231 breast cancer cell line carrying a tetracycline-inducible small hairpin RNA (shRNA) construct to knockdown endogenous TDRD3 levels." (PMID 28101374, 2017). "Here, we report TDRD3 as a novel regulator of cell proliferation and invasion in breast cancer cells." (PMID 28698590, 2017). "Knockdown of TDRD3 expression in breast cancer cells decreases the level of MCL-1, a known USP9X substrate, and sensitizes breast cancer cells to chemotherapy drug-induced apoptosis." (PMID 28101374, 2017). "We have documented in the current study a novel role for TDRD3 in promoting tumorigenesis and metastasis in breast cancer cells." (PMID 28698590, 2017). "Knockdown of TDRD3 expression in breast cancer cell lines decreases the expression of TDRD3 target genes, including the oncogene c-MYC." (PMID 28101374, 2017). "Taken together, our results show that TDRD3 can selectively promote translation of a specific subset of mRNAs in breast cancer cells." (PMID 28698590, 2017). "In cancer, elevated levels of TDRD3 form part of the gene expression signature that is used to predict an unfavorable prognosis for breast cancer patients." (PMID 28101374, 2017). "This is in consistent with the clinical observations that elevated TDRD3 level is one of the predictors of poor prognosis for breast cancer patients." (PMID 28101374, 2017). "SGs mediate cervical cancer cell metastasis by inhibiting ribonuclease inhibitor 1 (RNH1) to promote angiopoietin activity, while tudor domain containing 3 (TDRD3) located within SGs is one of the key factors promoting breast cancer cell invasion and lung metastasis." (PMID 37179344, 2023). "Finally, we show that knockdown of TDRD3 expression sensitizes breast cancer cells to chemotherapeutic drug-induced apoptosis, likely due to its regulation of USP9X." (PMID 28101374, 2017). "In highly aggressive breast cancer cells, knockdown resulted in decreased cell invasion and reduced lung metastasis, while in weakly metastatic cells, overexpression of TDRD3 was sufficient to confer to them the ability to invade through an extracellular-like matrix." (PMID 28698590, 2017). "So, it will be important in future studies to explore whether TDRD3 and specific PRMTs act in the same pathway(s) to promote breast cancer development and disease progression." (PMID 28698590, 2017). "Based on these results we next investigated whether TDRD3 could also affect cell proliferation in ER− breast cancer cells." (PMID 28698590, 2017). "We next examined whether knockdown of TDRD3 sensitizes MDA-MB 231 cells to the breast cancer chemotherapy drug, camptothecin (CPT)." (PMID 28101374, 2017). "Whether TDRD3’s function in breast cancer cell invasion and metastasis is dependent on its involvement in the trimeric complex will require further experimentation." (PMID 28698590, 2017). "Indeed, knockdown of TDRD3 expression sensitizes breast cancer cells to CPT-induced apoptosis." (PMID 28101374, 2017). "Since increased MYC expression is oncogenic and a driver of uncontrolled cell proliferation in many cancers including breast cancer, it is conceivable that TDRD3 may regulate breast cancer cell proliferation and tumor growth at least in part through this pathway." (PMID 28698590, 2017).
breast carcinoma (continued). "Altogether, these results indicate that an intact TDRD3, capable of taking part in interactions with for example TOP3β, components of the EJC, and/or FMRP, is required to promote cell invasion in breast cancer cells." (PMID 28698590, 2017). "We report here that TDRD3 promoted efficient cell growth in ER+ MCF7 cells, but importantly, it also exerted this effect in two different ER− breast cancer cell lines." (PMID 28698590, 2017). "Taken together, these results indicate that TDRD3 can regulate cell growth regardless of estrogen receptor status in breast cancer cells." (PMID 28698590, 2017). "Therefore, our study identifies TDRD3 as a regulator of USP9X and a potential target for therapeutic induction of apoptosis in breast cancer cells." (PMID 28101374, 2017). "Recent in vitro studies on the transcriptional co-activator TDRD3—a Tudor-domain protein that binds to H4R3me2a—show that this protein binds to the TSS regions of certain genes in human breast cancer cells; however, no significant enrichment was detected on the non-methylated alleles of human ICRs." (PMID 24097435, 2014). "Because TOP3B has been reported to be ubiquitylated and targeted for proteasomal degradation in MCF7 breast cancer cells in the absence of TDRD310, we measured the ubiquitylation of TOP3B in TDRD3-depleted cells (i.e., in siTDRD3-transfected HEK293 cells and in TDRD3KO HCT116 cells)." (PMID 37980342, 2023).
Cognitive impairment (3 papers, 2022 to 2024). Abnormal cognition is characterized by deficits in thinking, reasoning, or remembering. "Characterization of TOP3B or TDRD3 knockout mice suggested defective neuronal activity-dependent transcription as well as defective post-transcriptional regulation as mechanisms behind the cognitive impairment." (PMID 38534397, 2024). "We infer that the entire Top3b-Tdrd3 complex is essential for normal brain function, and that defective post-transcriptional regulation could contribute to cognitive impairment and psychiatric disorders." (PMID 36909584, 2023). "The findings that two major interacting partners of TDRD3, TOP3B and FMRP, are linked to psychiatric and cognitive disorders imply that TDRD3 itself could be associated with the same disorders." (PMID 36909584, 2023). "A major objective of this study is to establish a mouse model to examine a hypothesis that Tdrd3 may resemble its two partners (Top3b and FMRP) in playing important roles in psychiatric and cognitive disorders." (PMID 36909584, 2023). "TDRD3 is part of the TOP3beta-TDRD3-FMRP complex, and TOP3beta deletion was recently linked with schizophrenia, cognitive impairment, and learning difficulties, while lack of FMRP causes the Fragile X syndrome characterized by severe learning deficits and mental retardation." (PMID 35974141, 2022).
fragile X syndrome (3 papers, 2018 to 2022). A genetic syndrome caused by mutations in the FMR1 gene which is responsible for the expression of the fragile X mental retardation 1 protein. "Mutation of TDRD3 is associated with human Fragile-X syndrome and primary ovarian insufficiency." (PMID 29954329, 2018).
schizophrenia (2 papers, 2022 to 2023). A major psychotic disorder characterized by abnormalities in the perception or expression of reality. "Similarly, human TDRD3 genomic variants have been associated with schizophrenia, verbal shorten-memory and learning, and educational attainment." (PMID 36909584, 2023).
Anxiety (1 paper, 2023). Intense feelings of nervousness, tension, or panic often arise in response to interpersonal stresses. "For example, Tdrd3-null mice exhibit reduced anxiety in several behavior assays, which is opposite to Top3b-null mice, which show increased anxiety." (PMID 36909584, 2023). "Collectively, these results indicate reduced anxiety in Tdrd3-null mice, a phenotype that is directly opposite to Top3b-null mice, which show increased anxiety in a nearly identical battery of tests." (PMID 36909584, 2023). "Although increased time in the center of open field could reflect reduced anxiety of Tdrd3-null mice, it is possible that it could also be a simple consequence of increased overall physical activity, as measured by total distance traveled in the open field." (PMID 36909584, 2023). "We gave Tdrd3-null mice a panel of behavior tests to examine whether they exhibit cognitive and anxiety abnormalities comparable to Top3b-null and other mouse models of psychiatric disorders." (PMID 36909584, 2023). "Together, these data suggest that Tdrd3-null mice have reduced myelination and increased axon density in CC, both of which may contribute to the reduced anxiety and impaired cognitive behaviors." (PMID 36909584, 2023). "The defects found only in Tdrd3-null mice include reduced anxiety and myelination as well as elevated neuron complexity, suggesting that Tdrd3 may also have function(s) independently of Top3b." (PMID 36909584, 2023).
colon cancer (1 paper, 2024). "A study of TOP3B or TDRD3 knockout in human HCT116 colon cancer cells indicated that TOP3B–TDRD3 can regulate mRNA translation and turnover with mechanisms that may not always depend on the TOP3B topoisomerase activity." (PMID 38534397, 2024).
enteroviral infection (1 paper, 2022). "We hypothesized that if TDRD3 indeed plays a significant role in antiviral immunity during enteroviral infection, then enteroviruses may have evolved to counteract TDRD3 function." (PMID 35085371, 2022).
immune deficiency (1 paper, 2026). "Notably, a TDRD3 inhibitor has recently been developed, which could be leveraged to enhance immune activation, potentially offering promising avenues for treating immune deficiency or boosting antitumor responses." (PMID 41576154, 2026).
lung adenocarcinoma (1 paper, 2017). A carcinoma that arises from the lung and is characterized by the presence of malignant glandular epithelial cells. "In the human VMRC-LCD lung adenocarcinoma cell line, both alleles of TDRD3 are missing." (PMID 28101374, 2017).
Splenomegaly (1 paper, 2026). Abnormal increased size of the spleen. "In addition to reduced body weight, old but not young Tdrd3-deficient Treg mice also exhibited splenomegaly, with markedly increased spleen weight and total cellularity, together with an increased CD3+ T cells, including both CD4+ and CD8+ subsets." (PMID 41576154, 2026).
triple-negative breast carcinoma (1 paper, 2017). An invasive breast carcinoma which is negative for expression of estrogen receptor (ER), progesterone receptor (PR), and human epidermal growth factor receptor 2 (HER2). "Next, we sought to determine whether TDRD3 was required to maintain the highly metastatic properties of triple-negative breast cancer cells." (PMID 28698590, 2017).
virus infection (1 paper, 2022). "To examine TDRD3 in the context of virus infection, we next sought to determine if TDRD3 itself is recruited to virus-induced SGs." (PMID 35085371, 2022). "Virus replication is enhanced in the absence of both TDRD3 and G3BP1, and virus infection leads to cleavage of TDRD3 by the enterovirus proteinase 2A." (PMID 35085371, 2022).
cancer (7 papers, 2015 to 2025). A tumor composed of atypical neoplastic, often pleomorphic cells that invade other tissues. "Tudor domain-containing protein 3 (TDRD3) mediates transcriptional activation in nucleus and formation of stress granules in the cytoplasm, being implicated in cell proliferation and invasion in different types of cancer." (PMID 41302034, 2025). "In future experiments, it would be interesting to explore the potential beneficial effect of targeting and reducing TDRD3 expression in cancers known to be ‘addicted’ to MYC over-expression." (PMID 28698590, 2017). "Identification of TDRD3 as a regulator of USP9X is important because it provides an alternative pathway to target MCL-1 in cancer." (PMID 28101374, 2017). "We have previously shown that TDRD3 localizes to cytoplasmic stress granules, a structure shown to promote survival upon treatment with chemotherapeutic drugs in cancer cells." (PMID 28698590, 2017). "A previous study indicated that in stress granules, TDRD3 is located in the cytoplasm, and its Tudor domain which could recognize methylated motifs can promote survival upon treatment with chemotherapeutic drugs in cancer cells." (PMID 35710353, 2022). "It should be mentioned that mammalian Top3β-TDRD3 complex differs from its Drosophila counterpart in that it lacks stable association with AGO2, as evidenced by the absence of AGO2 in Top3β or TDRD3 immunoprecipitation from human cancer cell lines." (PMID 31683993, 2019).
infection (2 papers, 2014 to 2022). The state of being infected such as from the introduction of a foreign agent such as serum, vaccine, antigenic substance or organism. "Additionally, there was no apparent difference in enterovirus replication kinetics and host translation shutoff in high MOI infections, indicating potential functional coordination between TDRD3 and G3BP1 at the level of virus infectivity." (PMID 35085371, 2022). "To further test the hypothesis that TDRD3 may play an antiviral role during infection, particularly in the context of SGs and G3BP1, we infected HeLa cells with dsRed-expressing CVB3 at an MOI of 0.5 to generate multistep viral growth curves." (PMID 35085371, 2022). "Another example was the Tdrd3 gene, which showed differential isoform expression in CAST/EiJ mice on day 2 after MA15 infection." (PMID 24902603, 2014). "Indeed, we show here that TDRD3 itself is cleaved by enteroviral 2Apro, similar to 3Cpro-mediated cleavage of G3BP1 that restricts SG formation over the course of infection." (PMID 35085371, 2022).
tumor (2 papers, 2017 to 2024). "At endpoint (46 days), the mean tumor volume observed with TDRD3 knockdown cells was 14.5-fold smaller relative to controls." (PMID 28698590, 2017). "Specifically, dysregulation of TDRD3 expression altered cell proliferation in culture, with depletion impeding tumor xenografts growth in mice." (PMID 28698590, 2017). "Our study also demonstrates that TDRD3 depletion inhibits tumor formation and metastasis to the lung in vivo." (PMID 28698590, 2017). "In SHO mice, a significant impairment in tumor growth with TDRD3 knockdown was observed at 31 days post injection." (PMID 28698590, 2017). "The knockdown of TDRD3 in MDA MB 231 cells resulted in a significant decrease in xenograft tumor growth rate in both mouse models used." (PMID 28698590, 2017). "Moreover, TDRD3 depletion in these cells drastically impeded tumor growth in mouse xenograft experiments." (PMID 28698590, 2017). "Likewise, in the SHC mice, a significant decrease in tumor volume was observed with TDRD3 knockdown beginning at 38 days post-injection." (PMID 28698590, 2017). "Disruption of the H3Y99sulf-H4R3me2a-TDRD3 axis can inhibit the expression and functions of hypoxia-inducible factor 1-alpha and PDK1, resulting in suppressed proliferation, tumor growth, and survival of HCC cells suffering hypoxia stress." (PMID 38311175, 2024).
TDRD3 also shares sentences with these, for which no sentence is quoted: adenoma (1 paper); autism (1); breast tumors (1); cervical cancer (1); cognitive disorder (1); dementia (1); Infertility (1); mental retardation (1); polycystic ovary syndrome (1); psychiatric disorder (1).